BRAF (B-Raf proto-oncogene, serine/threonine kinase)
Diseases named in the same sentence as BRAF in open-access papers (continued):
Sharing a sentence is not in itself a finding about the gene and the disease.
tumor (continued). "The B cell/plasma cell score did not have significant association with any of the studied clinicopathological factors, including age, sex, tumor location, stage, grade, lymphovascular invasion, MMR status, and BRAF status (p > 0.05)." (PMID 36800011, 2023). "As such, through inhibition of BRAF and its downstream modulator MEK, TTs mediate tumour regression in responders through MAPK blockade." (PMID 36967556, 2023). "Immunohistochemistry staining showed the tumour was positive for AE1/3, CK7, GATA-3 and GCDFP-15; and was negative for CK20, PAX-8, CDX-2, WT-1, TTF-1, mammaglobin and BRAF V600E." (PMID 36871042, 2023). "In 62 (16%) of the 393 patients with NSCLC, the tumor had EGFR (46, 12%), ALK (8, 2%) or BRAF V600E (8, 2%) targetable genomic alterations." (PMID 37370865, 2023). "For CRCs, tumor anatomic site, stage, and molecular profiles, specifically microsatellite instability (MSI), KRAS, BRAF, and PI3K, aid in designing treatments." (PMID 36916704, 2023). "Regorafenib is an oral multi-target kinase inhibitor, which inhibits tumorigenesis, tumor angiogenesis and tumor microenvironment by targeting VEGFR1/2/3, TIE-2, BRAF, KIT, RET, PDGFR and FGFR." (PMID 36937443, 2023). "To assess immune effects of BRAF/MEK inhibition and the potential cooperativity with ICB, we implanted ABPS tumor cells subcutaneously into immune-competent C57BL/6 mice and treated them with vehicle, DT, anti-PD-1 antibody, or the combination." (PMID 36702949, 2023). "Focusing on CpG islands of all metabolic genes differentially expressed between BRAF- and RAS-like tumours (i.e., 459 genes) we found that about 30% of them display significant methylation changes (i.e., 144 genes, of which 48 hyper- and 96 hypomethylated)." (PMID 37198319, 2023). "This study verifies the effectiveness of Da in the treatment of BRAF V600E mutant DTC and the highly synergistic effect of Da and Dox co-delivery by tumor-targeted self-assembled peptides." (PMID 37153748, 2023). "To understand the effects of BRAF/MAPK inhibition specifically in tumor cells, we characterized gene expression changes after treatment in the tumor epithelial compartment to identify potential tumor cell-intrinsic mechanisms underlying patient response." (PMID 36702949, 2023). "Here, the authors describe a quantitative functional cancer genomics platform in genetically engineered mice, and uncover complex interactions between tumor suppressors and KRAS, BRAF, and EGFR oncogenes across more than 100 different lung tumor genotypes." (PMID 37828026, 2023). "A trend in responses toward “not a contraindication” was reported for lymph node positive primary tumour, molecular markers (MS stable/KRAS positive/BRAF positive) and raised tumour markers (CEA, CA19.9, CA125)." (PMID 37020095, 2023). "The preclinical data suggested that inhibition of BRAF and MEK pathway leads to increased activity of CD4 and CD8 T cells and thereby ability to destroy tumor cells." (PMID 37645429, 2023). "These neoplasms are frequently categorized based on specific genetic changes such as FGFR1, MYB/MYBL1, BRAF, or IDH1/2, identified through DNA methylation profiles." (PMID 38137148, 2023). "Since this is well in line with previous studies attesting similar effects to MAPK pathway inhibition with BRAF and MEK inhibitors, RSK seems to be an important mediator of the MAPK pathway induced immune evasive tumor state." (PMID 37464364, 2023). "The variables that were predictive of OS in the multivariable Cox model, at a cut-off of p < 0.05, were age, BRAF status, MMR status, AJCC stage, tumor differentiation, and receipt of chemotherapy." (PMID 38139338, 2023). "Currently, to better predict the behavior of a tumor, genetic alterations in KRAS, v-RAF, BRAF and CDX2 are used to guide prognostication and optimize adjuvant treatment." (PMID 37762323, 2023).
tumor (continued). "It functions by inhibiting the growth of tumor cells and the formation of blood vessels through targeting various serine/threonine and tyrosine kinases such as RAF1, BRAF, VEGFR 1, 2, 3, PDGFR, KIT, FLT3, FGFR1, and RET." (PMID 37299411, 2023). "Recurrent patients had higher mean protein expression of FoxP3, MAPK-activation markers (BRAF, p38-MAPK) and PI3K/Akt activation (phospho-Akt) within the tumor regions." (PMID 36980587, 2023). "Here we report—for the first time—a comprehensive investigation of all metabolic genes in TCGA-THCA cohort, focusing on a comparative analysis between BRAF- and RAS-like tumours." (PMID 37198319, 2023). "Dual BRAF/MEK inhibition also expanded memory and activated/exhausted CD8+ T cells, which was required for durable tumor regression to be elicited." (PMID 37834284, 2023). "Our study supports the value of tumour necrosis as an adverse prognostic factor in CRC independent of disease stage, lymphovascular invasion, tumour grade, MMR status, and BRAF status." (PMID 37031328, 2023). "Exposure to the clinically used combination of the BRAF-inhibitor dabrafenib and the MEK-inhibitor trametinib (DT) leads to rapid tumor regression, followed by a drug tolerant phase, from which resistance invariably develops." (PMID 37072838, 2023). "However, we can postulate that besides to influence tumor cells, molecules released by SA might reprogram CM microenvironment and/or reach the blood vessels to induce systemic modifications that would contribute to BRAF-mutant CM growth and treatment failure." (PMID 37386023, 2023). "To validate the excellent sensitivity (100%) of pan-TRK IHC in the 11 pan-TRK negative samples, we additionally performed FFPE-TLC in the high NTRK fusions prevalent (22%) subgroup of mCRC patients with a MSI-H/dMMR, BRAF, and RAS wild-type tumor." (PMID 37067589, 2023). "In a cohort with BRAF V600E WT SKCM, the two ICD-related subgroups were established, and the OS and tumor microenvironment of these subgroups were compared." (PMID 36704723, 2023). "Immunohistochemistry (IHC) revealed that the tumor cells in this lesion were positive for TTF-1, thyroglobulin, CK19, HBME-1, Galectin-3 and BRAF (V600E)." (PMID 37544981, 2023). "Finally, we are aware that the absence of molecular genetic variables such as RAS/BRAF-V600E mutations or data on circulating tumor DNA could explain the worse prognosis of some patients." (PMID 37027061, 2023). "Advanced tumor stage ATC, which has been considered inoperable, can now profit from BRAF inhibitors alone or BRAF/MEK inhibitors." (PMID 37510219, 2023). "Treatment of BRAF-mutant PTC cell lines with BRAF inhibitor decreased phosphorylation of MEK and subsequently ERK1/2, blocked cell cycle progression, and inhibited tumor xenograft growth." (PMID 36624452, 2023). "Regorafenib potently blocks several protein kinases that are involved in tumor angiogenesis (VEGFRs 1–3), oncogenesis (BRAF, RAF, RET, KIT), metastasis (FGFR, PDGFR, VEGFR3) and tumor microenvironment (TME) signaling (Tie2, CSF1R)." (PMID 37620408, 2023). "The trial also assesses the impact of peptide vaccination, BRAF inhibitors, and MEK inhibitors on the immune system using participant blood and tumor samples." (PMID 38105263, 2023). "Common somatic mutations between the primary and the respective recurrences were then sought in the CTCs (BRAF V600E, TERT C228T, and C250T), to confirm the origin of these circulating cells from the parental GBM tumor." (PMID 37373295, 2023). "Second, a prognosis model based on ICD-related genes is feasible for assessing the prognosis of both BRAF V600E WT and mutant SKCM, its influence on the tumor microenvironment, and immunotherapy response." (PMID 36704723, 2023). "In KIAA1549:BRAF fused pilocytic astrocytoma, Ccl2 is important for the recruitment of microglia and establishing a permissive TME for tumor growth." (PMID 37901250, 2023).
tumor (continued). "Regorafenib is an oral multi-kinase inhibitor that targets signaling pathways involved in tumor angiogenesis (VEGFR1-3 and TIE2), oncogenesis (KIT, RET, RAF1, and BRAF), and the tumor microenvironment (PDGFR, FGFR, and CSF1R)." (PMID 37869085, 2023). "These suggest that BRAF/MEK inhibitors and an immune-therapeutic modality can synergize for tumor suppression, leading to clinical trials." (PMID 37834284, 2023). "Furthermore, the molecular responses of high versus low grade tumor cells carrying the BRAFV600E mutation to BRAF and MEK inhibition have not been investigated in detail and thus the differential responses in patients with LGG and HGG to these therapies are poorly understood." (PMID 37920169, 2023). "NDRS cancer registrations have included somatic molecular data since 2016 and MSI, MMR IHC, BRAF and MLH1 methylation analysis is available for all tumours diagnosed from 2019 onwards." (PMID 36572524, 2023). "Tumor biopsies from primary tumor or metastases in formalin-fixed paraffin-embedded (FFPE) were obtained before study entry, for MSS, RAS and BRAF status." (PMID 36083313, 2023). "Thus, genetic heterogeneity within the tumour needs to be factored in when making a diagnosis, especially if the treatment involves therapeutic strategies that depend on the presence or absence of BRAF mutation." (PMID 37570213, 2023). "Within the population evaluable for response, one tumor was characterized as both RAS and BRAF mutant (BRAF MT) and was consecutively analyzed within the BRAF MT cohort." (PMID 35251955, 2022). "In another study, even short-term dual inhibition of BRAF/MEK, when combined with anti-PD-1, was sufficient to enhance tumour immune infiltration and overall improved tumour control in a CD8 + T-cell dependent manner." (PMID 35366166, 2022). "While substantial initial responses have been reported, the emergence of resistance to BRAF-targeting drugs is common, leading to reactivation of ERK through different mechanisms and, ultimately, tumor relapse." (PMID 36056964, 2022). "In the syngeneic YUMM1.7 model, we observed that the combination of BRAF and MEK inhibition delayed the tumor growth more significantly than the single agents, in accordance with recent studies." (PMID 35327519, 2022). "Persistent activation of BRAF leads to activation of the mitogen-activated protein kinase (MAPK) pathway, which finally enhances tumor progression." (PMID 35646190, 2022). "Initial findings for neoadjuvant BRAF plus MEK inhibitor therapy are encouraging, showing tolerability, delayed tumor recurrence, and complete pathological responses." (PMID 35513054, 2022). "The current mandatory biomarkers to look for in late-stage NS-NSCLC include different genomic alterations present on EGFR, ALK, ROS1, NTRK, BRAF, MET, and RET, as well as the PD-L1 expression of tumor cells." (PMID 35565387, 2022). "The same group also showed that tumor growth was reduced by single targeting of ERBB2 in cetuximab-resistant, quadruple (i.e., KRAS, NRAS, BRAF, and PIK3CA) wt CRC patient derived xenografts with ERBB2 mutations." (PMID 35582524, 2022). "For instance, patients with a BRAF V600E and RAS wildtype tumor seem to have a favorable prognosis compared to patients with a mutation in these genes, independently of mismatch repair status." (PMID 35565347, 2022). "Treatments using BRAF/MEKi or HCT, alone, resulted in a re-establishment of initial tumor volume, prior to the end of the study period, with HCT inducing resistance far earlier than BRAF/MEKi." (PMID 35494017, 2022). "In contrast, BRAF and KRAS alterations correlated with decreased tumor amplification burden in the TCGA dataset." (PMID 36171565, 2022). "Different factors, including performance status, age, tumor sidedness, biomarkers (such as RAS and BRAF), and microsatellite instability, can be used to guide treatment selection." (PMID 36147443, 2022).
tumor (continued). "In an immunocompetent murine model of orthotopic ATC, treatment with BRAF inhibitor PLX4720 alone, in combination with anti-PD-1, or with anti-PD-L1 antibody, led to significant tumor reduction of 41%, 61%, and 64%, respectively." (PMID 35992118, 2022). "The expression levels of oncogenes or tumor-related genes, such as BRAF, NOTCH3, and TERT, were higher in tumor tissues compared with paired normal tissues." (PMID 36092890, 2022). "Combined therapy using BRAF and MEK inhibitor seems to show a greater efficacy in the magnitude of reduction in tumor volume and in terms of rapidity of action compared to single-agent treatment." (PMID 35757402, 2022). "Nevertheless, Natale at al., propose that repeated pregnancies inhibit the growth of BRAF-driven human melanocytic neoplasia in xenografts and that GPER1 signaling promotes cell differentiation instead of proliferation, inhibiting tumor development." (PMID 35158973, 2022). "Here, we demonstrate that the tumor microenvironment protects CR-CSCs from EGFR/HER2, BRAF and PI3K targeting, promoting CD44v6 and Myc expression." (PMID 35158939, 2022). "A limitation of our findings is that it is unclear why BRAF and KRAS alterations would correlate with a decreased tumor amplification burden." (PMID 36171565, 2022). "SCH‐772984 is an ATP competitive ERK inhibitor, which effectively downregulates the MAPK/ERK signaling pathway in BRAF, MEK, and BRAF/MEK inhibitor‐resistant tumor models." (PMID 34614271, 2022). "First, the retrospective design of the study prevented us from properly investigating various clinical and histopathological parameters, including BRAF, MSI, PD-1 (CD279), PD-L1 (CD274), and the immunological profiling of the tumor." (PMID 36013050, 2022). "Plasma circulating tumor DNA (ctDNA) determination of RAS and BRAF has been shown to correlate well with tissue determination in multiple studies with different techniques." (PMID 35761123, 2022). "Adding cetuximab to vemurafenib in xenografts experiments resulted in increased antitumor activity and improved survival and combined administration of BRAF and EGFR inhibitors induces tumor regression in most patients." (PMID 35582524, 2022). "In this study, we analyzed the tumor growth velocity (TGV) of pLGG to investigate the impact of resection extent, tumor location and the most frequent BRAF aberrations on postoperative growth following IR." (PMID 36319795, 2022). "Sufficient tumor material was available from fourteen patients treated with certolizumab (14/18; 78%) for EGFR, KRAS, BRAF, ERBB2, and ALK testing and from ten patients (10/18; 56%) for NGS." (PMID 36241629, 2022). "Interestingly, recent studies have discovered some overlap in molecular profiling between LGG and HGG, and BRAF V600E and FGFR1 mutations can be found both in LGG and HGG, suggesting that LGG and HGG might share a similar biological mechanism of tumor pathogenesis." (PMID 35884462, 2022). "The population analyzed in this article comprises 717 patients with known exact primary tumor location and with RAS/BRAF wild-type tumors." (PMID 35158793, 2022). "One patient who received BRAF/MEK-inhibitors died between two outpatient clinic visits, and it was unclear if the anti-tumor treatment was stopped prior to death." (PMID 35247992, 2022). "Therefore, BRAF V600E expression was positive and tumor invasiveness could be related." (PMID 35356255, 2022). "Like CDK4/6i, BRAF and MEK inhibitors (BRAFi + MEKi), which inhibit the MAPK/ERK pathway, were originally developed to block tumor cell proliferation and survival, but were subsequently discovered to augment anti-tumor immunity." (PMID 35444175, 2022).
tumor (continued). "Although the clinical efficacy of BRAF/MEK inhibitor agents has been shown in treatment of PCPs, all previously published reports described its administration in settings of tumor recurrence or as adjuvant therapy." (PMID 35757402, 2022). "A fusion involving BRAF was detected in one tumour (DNA methylation score of 0.58 for LGG‐DNT) and represented the unique BRAF disruption identified in this cohort of specific DNTs." (PMID 35836307, 2022). "Sorafenib can resist tumor by inhibiting the expression of CD31, alphaSMA, pERK, VEGF, PDGF, TNFalpha, eNOS and HIF-1α/SLC7A11, BRAF/MAPK signaling pathways." (PMID 36544713, 2022). "The concurrent inhibition of BRAF and MEK proteins of the MAPK pathway decreases MAPK-driven acquired resistance, leading higher rate of tumor responses, more durable responses, and improved progression-free and overall survival rates." (PMID 36077374, 2022). "Specifically, BRAF and EGFR inhibition results in persistent inhibition of MAPK signaling and tumor growth." (PMID 36077604, 2022). "Thus, when evaluating the results of the study it is necessary to consider the intratumoral heterogeneity and the possibility that in the context of the tumor mass there could be subclones lacking the BRAF mutation or resistant subclones." (PMID 36686797, 2022). "In mouse models, inactivating Cdx2 in the context of oncogenic BRAF (BRAFV600E, mouse-human hybrid version of the V600E oncogene) leads to serrated lesions and tumor development." (PMID 35975243, 2022). "For example, tumor-infiltrating T cells surge when BRAF inhibitors and anti-PD1 antibodies are combined, prolonging survival and slowing tumor growth, as revealed by a BRAFV600E/PTEN-/- syngeneic tumor graft immunocompetent mouse model." (PMID 36358912, 2022). "More and more tumor biomarkers, such as PD-L1, BRCA1/2, BRAF, HER2, etc., have been discovered, which become an indispensable tool in current tumor treatment due to its ability to assist various clinical decisions." (PMID 35668930, 2022). "The rationale for this combination relies on the fact that treatment with BRAF and MEK inhibitors results in a more immuno-responsive tumor microenvironment." (PMID 36358912, 2022). "Of all patients with full tumour testing completed (dMMR/MSI and where needed, a BRAF V600E or MLH1 hypermethylation test), a result indicating high LS risk was present in 5% (74/1371)." (PMID 35509103, 2022). "A recent study firstly provided longitudinal evidence on molecular markers (including BRAF V600E, CIMP, and MLH1 methylation) of SPs, suggesting that epigenetic defect of MLH1 methylation was in relation to subsequent advanced neoplasms." (PMID 35402217, 2022). "Dabrafenib and trametinib are targeted drugs targeting BRAF and MEK1/2 belonging to the serine/threonine kinase family of the RAS pathway, respectively, which inhibit tumor cell proliferation by blocking the RAF-MEK-ERK signaling pathway." (PMID 36612173, 2022). "For each patient, before treatment, a blood sample will be obtained and analyzed for circulating free tumor DNA according to NGS (Foundation/Roche), to identify RAS/BRAF WT patients to be enrolled." (PMID 35832541, 2022). "Differentiated information on precise tumor location (isthmus, upper lobe), ETE, or molecular genetic processing, including BRAF analysis, is missing." (PMID 36135042, 2022). "Unfortunately, the onset of resistance to first line BRAF inhibitors is a common outcome, thought to be due to reactivation of the MEK pathway, as occurs in other tumours." (PMID 36582791, 2022). "RAS and BRAF mutations are both associated with a poor prognosis and are mutually exclusive, lending additional support to the hypothesis that an activating mutation in either gene is sufficient to promote tumorigenesis by increasing MAPK signalling and is also related to MSI tumours." (PMID 35207616, 2022).